CTLA4 (cytotoxic T-lymphocyte associated protein 4)
Diseases named in the same sentence as CTLA4 in open-access papers (continued):
Sharing a sentence is not in itself a finding about the gene and the disease.
melanoma (continued). "For instance, in melanoma, using dacarbazine alongside ipilimumab (an anti-CTLA-4 antibody) led to better outcomes than using dacarbazine alone." (PMID 39001539, 2024). "In 2011, ipilimumab, called Yervoy, which was a whole human monoclonal antibody against CTLA-4, was approved for the treatment of melanoma as the first CTLA-4 mab." (PMID 39238638, 2024). "In a rearranged during transfection (RET) melanoma mouse model, a 2-week broad-spectrum antibiotic regimen in germ-free and specific pathogen-free mice led to reduced anti-CTLA4 effects." (PMID 38617537, 2024). "In the phase III CheckMate 067 trial (NCT01844505) in advance melanoma, durable clinical benefit was demonstrated with nivolumab (anti-PD-1) plus ipilimumab (anti-CTLA4) combination over monotherapy with nivolumab or ipilimumab." (PMID 38646546, 2024). "Case presentation: This study investigated the role of the gut microbiota during the onset and remission of irAE enteritis in a patient with stage IV melanoma undergoing anti-PD-1 and anti-CTLA-4 therapy." (PMID 38965595, 2024). "A recent study reported the development of T2DM in melanoma patients receiving anti-CTLA-4 immunotherapy for a long time." (PMID 38313367, 2024). "Clinically, elevated serum levels of MIF have been observed in patients with advanced melanoma and correlate with poor response to anti-CTLA-4 therapy." (PMID 39028303, 2024). "PD-1 inhibitors, targeting PD-L1, have been found to be more effective and less toxic than CTLA4 inhibitors in melanoma, indicating the importance of the PD-1/PD-L1 pathway in immunotherapy." (PMID 38713378, 2024). "Ipilimumab, an antibody targeting CTLA-4, was the first immune checkpoint inhibitor authorized for cancer therapy and has been particularly effective in melanoma." (PMID 39483536, 2024). "One of these innovative medications is ipilimumab, an anti-CTLA-4 monoclonal antibody that has become a mainstay in the arsenal of treatments for cancer, including esophageal, renal, and melanoma." (PMID 38931856, 2024). "The combination of immune checkpoint inhibitors targeting cytotoxic T lymphocyte-associated antigen 4 (CTLA-4) and programmed death 1 (PD-1) has demonstrated heightened efficacy in advanced melanoma, albeit with notable side effects." (PMID 38931856, 2024). "A phase I clinical trial targeting 22 patients with multiple melanoma metastases was conducted using hypofractionation radiotherapy (8 GyX3) combined with anti-CTLA4 antibody ipril monoclonal antibody." (PMID 38339426, 2024). "It has also been noted that the use of anti-CTLA-4 inhibitors results in an increased expression of PD-1; hence, using combination therapy results in a more robust treatment response in patients with melanoma." (PMID 38410760, 2024). "The introduction of anti-CTLA-4 and anti-PD-1 checkpoint inhibitors has significantly improved overall survival for patients with advanced melanoma." (PMID 39769318, 2024). "Pembrolizumab or nivolumab is often used in combination with CTLA-4 immune checkpoint inhibitors, and its clinical benefit in patients with metastatic or advanced melanoma has been noted in numerous literature." (PMID 39530091, 2024). "They further observed that secretomes from human metastatic melanoma cells suppressed CTLA-4 mRNA through miR-155 while simultaneously increasing FOXP3 expression in human Treg cells." (PMID 38462628, 2024). "Despite serving as the first-line treatment for melanoma, combination therapy with PD-1 and CTLA-4 blockade was ineffective in 40% of treatment-naive patients with melanoma." (PMID 39436696, 2024). "Given the efficacy of PD-L1 and CTLA4 inhibitors in various cancers, especially in melanoma and certain subsets of breast and cervical cancers, a bispecific antibody targeting both CD274 and CTLA4 has a strong rationale." (PMID 38713378, 2024).
melanoma (continued). "In the melanoma GSE91061 cohort (treated with anti-PD-L1 and anti-CTLA4 immunotherapy), patients with PR/CR had a lower risk score compared to those with SD/PD, although this difference was not statistically significant." (PMID 39015573, 2024). "The majority of patients received combination therapy with anti-PD-1/L1 and anti-CTLA-4 (49.3%), and the most common malignancy treated was melanoma (37.6%)." (PMID 38791997, 2024). "By blocking this checkpoint, anti-CTLA-4 therapies such as ipilimumab amplify T-cell activation and proliferation, significantly enhancing the immune system's ability to target and destroy melanoma cells." (PMID 39229331, 2024). "It is imperative to expand the study of T-VEC to other stages of melanoma as well to use it as a combinatory treatment with PD-1 inhibitors or CTLA-4 inhibitors." (PMID 38921005, 2024). "Vitiligo-like lesions occur with an incidence of up to 25% under anti-PD1 (e.g., pembrolizumab and nivolumab), PDL1 (e.g., atezolizumab), and CTLA4 (e.g., ipilimumab) treatments that target immune privilege checkpoints for advanced melanoma and other cancers." (PMID 38673994, 2024). "Immune checkpoint inhibitors, which are primarily used to treat melanoma, target two main proteins: PD-1 with monoclonal antibodies like nivolumab and pembrolizumab, and CTLA-4 with ipilimumab." (PMID 39026661, 2024). "The treatment landscape for melanoma has been revolutionized with the introduction of immunotherapies, particularly checkpoint inhibitors targeting CTLA-4 and PD-1/PD-L1 pathways." (PMID 39229331, 2024). "In a study of melanoma, anti-CTLA-4 treatment specifically enhanced intratumoral CD8+ T cells with increased activation status (CD44, CD69 & Tbet expression) compared to those in the draining lymph node." (PMID 39247203, 2024). "Some phase I and II trials showed disease stabilization in various malignancies, and the phase Ib trial (NCT03293784) combining TNF inhibitor certolizumab with anti-PD-1/anti-CTLA-4 in melanoma patients demonstrated safety and high response rates." (PMID 39206193, 2024). "Recently, IDO1 inhibitors have been included in clinical trials in combination with chemotherapy and immunotherapy, such as anti-CTLA-4 and/or PD-1, to restore anti-melanoma immunity." (PMID 38791968, 2024). "The Food and Drug Administration’s 2011 approval of ipilimumab, an anti-CTLA-4 antibody, marked a milestone for advanced melanoma patients, demonstrating extended survival in a Phase III trial." (PMID 38517331, 2024). "While immunotherapy, especially immune checkpoint inhibitors (ICIs) targeting CTLA-4 and PD-1, has transformed melanoma management, many patients experience limited responses or develop resistance, highlighting the need for new therapeutic strategies." (PMID 39743998, 2024). "Cancer treatments for melanoma and non-small-cell lung cancer involve blocking CTLA-4, PD-1, and PD-L1 receptors." (PMID 39328455, 2024). "The CHECKMATE-067 trial demonstrated that the combination of CTLA-4 and PD-1 inhibitors (ipilimumab and nivolumab) offers a significant survival advantage in advanced melanoma patients." (PMID 38474231, 2024). "After a decade of clinical testing, Ipilimumab, an anti-CTLA-4 antibody, was proven to improve melanoma patient survival in a large Phase III clinical trial and became the first checkpoint inhibitor approved by the FDA for advanced melanoma." (PMID 39194710, 2024). "In Zhao2019_PD1-Glioblastoma and Gide2019_PD1+CTLA4-Melanoma cohorts, high-CD44-expression patients exhibited the unfavorable OS relative to low-CD44-expression counterparts, representing a worse immunotherapy outcome." (PMID 38590654, 2024). "In the melanoma anti-CTLA4 cohort, the AUC of CD44 was 0.8, indicating a higher predictive ability than any other marker, except MSI (AUC = 0.9)." (PMID 38590654, 2024).
melanoma (continued). "In a previous study, high-serum VEGF levels were correlated with poor clinical outcomes in patients with melanoma treated with anti-CTLA-4 antibodies, and patients with high-serum VEGF levels had a significantly lower rate of disease control." (PMID 39682145, 2024). "While many ICI combinations have proved successful in preclinical models, Probody Therapeutics with combined anti-PD-1 and anti-CTLA-4 is currently in a phase III clinical trial (CheckMate 067) in advanced melanoma patients." (PMID 39247203, 2024). "These techniques have demonstrated remarkable success in melanoma, with immune checkpoint inhibitors like anti-PD-1 and anti-CTLA-4 antibodies standing out due to their efficacy." (PMID 38835341, 2024). "Pembrolizumab and nivolumab target PD-1 to enhance the immune response against melanoma cells, whereas ipilimumab binds to CTLA-4 to support the immune response." (PMID 38715609, 2024). "Combination therapy targeting MCL-1 and Bcl-xL effectively eliminates melanoma cells from patients who experience relapse after PD-1 or CTLA-4 remedy, and curtails the self-renewal capability of melanoma cells." (PMID 39403382, 2024). "Immunotherapies, particularly ICIs that target immunomodulatory receptors CTLA-4 and PD-1, or the ligand PD-L1, have transformed the landscape of melanoma treatments." (PMID 38673829, 2024). "This protective effect of anti-CTLA4 correlates with a systemic expansion of Tregs, both in the animal model and in patients with melanoma." (PMID 39737964, 2024). "Disease-related research focuses primarily on melanoma, drug-related research on anti-CTLA-4 monoclonal antibodies and anti-PD-1 monoclonal antibodies, and adverse events research on autoimmune hypophysitis and diabetes." (PMID 38686201, 2024). "Based on these molecular mechanisms of immune interactions with cancer, clinical trials based on checkpoint inhibition therapy against CTLA-4 and/or PD-1 versus PD-L1 have been successful in the treatment of melanoma, lung cancer and other types of cancer." (PMID 39155358, 2024). "Survival analysis underscored a significant association between high FCN1 expression and prolonged OS in PD1-treated ccRCC and CTLA4-treated melanoma cohorts." (PMID 39139822, 2024). "In the B16-F10/GVAX melanoma model, we found that both the anti-CTLA-4 VHH-VHHkappa and anti-PD-L1 VHH-VHHkappa conjugates were effective in controlling tumor growth and improving survival." (PMID 39149504, 2024). "CTLA-4 inhibitors, such as ipilimumab, have demonstrated favorable efficacy in the treatment of melanoma, colorectal cancer (CRC), and hepatocellular carcinoma (HCC)." (PMID 38983866, 2024). "In melanoma, the combination of CTLA-4 and PD-1 inhibition has a higher efficacy than either therapy alone but is associated with a 55% rate of severe irAEs." (PMID 38339253, 2024). "This dataset encompasses expression data from 47 melanoma patients who underwent treatment with PD-1 immune checkpoint inhibitors or CTLA-4 immune checkpoint inhibitors." (PMID 38665430, 2024). "Because upfront treatment with ICI, most often combined PD-1/CTLA-4 blockade, is standard in patients with advanced melanoma, the question arises as to the optimal therapy for those patients who do not respond to ICI or experience disease progression." (PMID 39801681, 2024). "In patients with melanoma treated with anti–PD-1 and anti–CTLA-4, DNA-PK (PRKDC) transcript levels inversely correlated with CD8 and MHC-I transcript levels, whereas mutations in DNA-PK correlated with increased tumor mutation burden (TMB) and neoantigen load." (PMID 39436696, 2024). "In contrast, supplementation with susceptible Bacteroides fragilis in germ-free or antibiotic-treated melanoma mice accentuated the therapeutic effects of anti-CTLA4." (PMID 38617537, 2024). "Fifty-three patients with unresectable Stage III or Stage IV melanoma treated with anti-LAG-3 in combination with anti-PD-1 ± anti-CTLA-4 were included in this study." (PMID 37808404, 2023).
melanoma (continued). "Many drugs targeting CTLA-4/PD-1 have been approved for the treatment of different types of cancers, including melanoma, lung, breast, bladder, and gastric cancer, classic Hodgkin’s lymphoma, and B-cell lymphoma." (PMID 37370399, 2023). "This OV was one of the first engineered viruses to express mAbs against immune checkpoints (CTLA-4 and PD-L1), initially tested in a melanoma model." (PMID 37190279, 2023). "Nevertheless, only a fraction of patients responds to monotherapy; the combination of CTLA-4 and PD-1 blockers showed a remarkable increase in response rates and median survival time in melanoma and renal cell carcinoma." (PMID 37370399, 2023). "The United States Food and Drug Administration (FDA) has approved several related drugs that target CTLA-4, PD-1, and its ligand PD-L1, for the treatment of advanced melanoma, non-small cell lung cancer, Hodgkin’s lymphoma, and head and neck cancer." (PMID 37251931, 2023). "In the combination group (PD-[L]1/CTLA-4; n = 39), melanoma (56.4%) and RCC (12.8%) were the most common cancers." (PMID 37335906, 2023). "Patients with melanoma in this cohort were treated with anti-PD-1 monotherapy (n = 63) or combined anti-PD-1 and anti-CTLA-4 therapy (n = 57)." (PMID 37547288, 2023). "To analyze the efficacy of anti-PD-1 and anti-CTLA4 treatments in different cancer subtypes, we extracted data on immunotherapy in melanoma patients as a reference, and 47 immunotherapy patients were included in the analysis." (PMID 37674202, 2023). "On the contrary, in a study on the treatment of melanoma patients with CTLA‐4 inhibitors, it was found that patients with effective tumor remission were more likely to develop autoimmune toxicity." (PMID 37724594, 2023). "Further identification of co-factors that regulate CTLA4 mRNA stability in Treg cells from melanoma patients is needed to fully understand the mechanisms involved." (PMID 37197667, 2023). "Initial clinical trials in malignant melanoma treated with CTLA-4 antibodies reported irAE in about one third of patients who were shown to have clinical response." (PMID 37291665, 2023). "The next widely used drug at the secondary treatment following previous PD-1 or PD-L1 therapy, especially in melanoma patients, was a CTLA-4 inhibitor ipilimumab." (PMID 37444600, 2023). "In the last 10 years, immune checkpoint blockades (ICBs) including PD-1/PD-L1 and CTLA-4 inhibitor has been shown to be effective against melanoma." (PMID 37495610, 2023). "Ipilimumab boosts the immune system's reaction to cells of melanoma and tumors by inhibiting CTLA-4." (PMID 37803407, 2023). "For example, genetic ablation of SK1 slowed melanoma tumor growth and enhanced the antitumor activity of antibodies against CTLA-4 or PD-1 in C57BL/6 mice by increasing the CD8/Treg ratio in the tumors." (PMID 38069222, 2023). "According to the results, the transcriptome profiles of C3 and melanoma patients who responded to anti-CTLA4 immunotherapy were highly similar (P = 0.006, Bonferroni adjusted P = 0.072, FDR adjusted P = 0.072)." (PMID 36949954, 2023). "Melanoma is highly reactive to checkpoint inhibitors, and CTLA-4 and PD-1 are representative immune checkpoint molecules." (PMID 38203530, 2023). "Previous studies have identified that BTLA can suppress the proliferation of Vδ2 T cells, while blocking the PD-1 and CTLA-4 pathways can restore T cell function and improve survival in melanoma, colon carcinoma, and ovarian carcinoma." (PMID 38077396, 2023). "PD-1, PD-L1, and CTLA-4 inhibitors display encouraging therapeutic effects among common ICIs, some of which have been ratified to treat melanoma, non-small-cell lung cancer, kidney cancer, and bladder cancer." (PMID 36726489, 2023). "Six hundred fourteen patients with cancer (esophageal, gastric, head and neck, lung, melanoma, renal cell, urothelial, and other cancer) received anti‐PD‐1, anti‐PD‐L1, or anti‐CTLA‐4 plus anti‐PD‐1 therapy." (PMID 37986680, 2023).
melanoma (continued). "After ipilimumab (anti-CTLA-4) treatment, patients with melanoma had an increased absolute lymphocyte count (ALC) and delayed enhancement of CD4+ and CD8+ T cells, which was associated with a positive outcome." (PMID 38328405, 2023). "Subsequently, we compared the expression profile of TCGA-PAAD patients with a melanoma dataset containing 47 patients who received anti-PD-1 and anti-CTLA-4 treatments." (PMID 37330494, 2023). "Immune checkpoint inhibitors (ICIs) that abrogate CTLA-4 and PD-1 are now the standards of care for advanced melanoma." (PMID 36674809, 2023). "Further studies have published similar results upon co-administration of A2AR antagonists and anti-PD-1 anti-CTLA-4 mAbs melanoma mouse models." (PMID 37345056, 2023). "Elevated baseline sPD-L1 levels also indicated poor efficacy in patients with melanoma treated with CTLA-4 or PD-1 blockades." (PMID 36639643, 2023). "In patients with bladder cancer, breast cancer, non-small cell lung cancer (NSCLC), and melanoma treated with anti-CTLA-4 immunotherapy, increased levels of ICOS+CD4+ T cells in tumor tissue and peripheral blood were detected." (PMID 37259155, 2023). "Anti-CTLA-4 and anti-PD-1/PD-L1 checkpoint inhibitors have shown promise in the treatment of melanoma, non-small-cell lung cancer, and bladder cancer." (PMID 37345057, 2023). "To verify our new finding in blood CTLA4 levels and their prognostic values, we performed another study using the US melanoma cohort, shown in the flow chart." (PMID 37197667, 2023). "In the melanoma cohort, anti‐CTLA‐4 monotherapy correlated with the longest median OS (95% CI) of 73.10 (68.70–NR) months." (PMID 37962239, 2023). "CTLA4/PD-1 therapeutic antibodies have already been sanctioned for melanoma, non-small cell lung cancer, and kidney cancer." (PMID 38116315, 2023). "For instance, in the context of investigating melanoma or prostate cancer, it was discovered that tumors that initially increased their levels of CTLA-4 and were later treated with anti-CTLA-4 antibodies subsequently raised their VISTA expression." (PMID 38001644, 2023). "Multiple studies have reported that high TCR repertoire diversity associates with improved survival in multiple tumors, and response to CTLA-4 inhibition in melanoma and hepatocellular carcinoma." (PMID 37100920, 2023). "Of note, this phenomenon of opposite prognostic and predictive value was present with regard to CTLA4 methylation in melanoma and clear cell renal cell carcinoma." (PMID 37259155, 2023). "In 2011 the FDA granted an initial approval for ipilimumab, an antibody drug targeting CTLA-4, making ipilimumab the first immunotherapy drug approved for the treatment of melanoma." (PMID 37929901, 2023). "Anti-PD-1 antibodies, however, have become the gold standard treatment for melanoma based on studies comparing anti-PD-1 to anti-CTLA-4 and to chemotherapy." (PMID 37900283, 2023). "Combined treatment with the glutaminase inhibitor CB-839 and PD-1 or cytotoxic T-lymphocyte-associated protein 4 (CTLA4)-targeted therapy increased antigen-specific T-cell infiltration and inhibited tumor growth in a melanoma model." (PMID 37291128, 2023). "Phs001493 (Renal cell carcinoma, Anti-PD1 therapy) and PRJEB23709_ipiPD1 (Melanoma,anti-CTLA4 & AMP; Anti-pd1 dual antibody therapy) were significantly associated with worse prognosis." (PMID 36647156, 2023). "Immune checkpoint receptors including CTLA-4 and PD-1 have been established as main therapeutic targets for immunotherapy of melanoma." (PMID 37122748, 2023). "The same results were also observed for triple-negative breast cancer and melanoma, including anti-CTLA-4 therapy-resistant type melanoma." (PMID 37568716, 2023). "Their study revealed that inhibition of the MIF blockade in combination with ipilimumab (anti-CTLA-4) improved the response to anti-CTLA-4 treatment in resistant melanoma." (PMID 37725261, 2023).